CSF1 (colony stimulating factor 1)
Diseases named in the same sentence as CSF1 in open-access papers (continued):
Sharing a sentence is not in itself a finding about the gene and the disease.
melanoma (continued). "Furthermore, a recent study describing T cell-induced release of CSF-1 as a CD8+ T cell-dependent adaptive resistance mechanism in melanoma highlights the importance of macrophage depletion in tumors refractory to ICB." (PMID 33924237, 2021). "However, at least 10 clinical trials have been conducted using high dose CSF1 therapy in cancer patients, including melanoma, refractory solid tumours, lymphoma and leukaemia." (PMID 33402221, 2021). "In the presence of anti-tumor monoclonal antibody (mAb), human monocytes cultured with macrophage colony-stimulating factor (M-CSF, also referred as CSF-1) phagocytose melanoma and neuroblastoma tumor cells, a process known as ‘antibody-dependent cellular cytotoxicity’ (ADCC)." (PMID 34359674, 2021). "sEVs of hypoxic melanoma, squamous skin carcinoma and lung cancer cells are loaded with immunosuppressive proteins like colony-stimulating factor 1 (CSF-1), C-C motif chemokine 2 (CCL2), ferritin heavy chain (FTH), ferritin light chain (FTL) and TGF-β as well as the miRNA let-7a." (PMID 32709110, 2020). "CSF-1 is an example of molecule with an established role in controlling proliferation, differentiation and survival of macrophages that is involved in melanoma progression and immune escape." (PMID 33212945, 2020). "CSF1 inhibitors also showed additive effects with ACT therapies in preclinical melanoma studies, where anti-CSF1 dampened myeloid cell-mediated immunosuppression in the TME, permitting greater CD4+ and CD8+ T-cell infiltration into tumors and with improved functionality." (PMID 30191140, 2018). "Furthermore, one report has demonstrated that CSF1 could promote melanoma resistance to PD1 checkpoint blockade, and many reports have shown that CSF1R targeting may be beneficial by showing strong anti-tumor effects." (PMID 32582282, 2020). "Moreover, the expression of CSF-1 on tumor cells in melanoma and NSCLC patients correlated with the enrichment of MDSC that could be inhibited in vitro by the blockade of CSF-1/CSF-1R signaling." (PMID 29942309, 2018). "As a methodology, SFD is able to reveal well-known proteins in melanoma exosomes that are immune-related and are also surface-expressed proteins, such as CD26 (DPP4), CD44, CALR, B7-H3 (CD276), CSF1, ICAM1, L1CAM, MICB, APOH, TIMP1, and CD39." (PMID 40805206, 2025). "Utilizing melanoma and NSCLC cell lines we show that CD1c+CD14+ cells emerge from cDC2s but not monocytes, through IL-6 and macrophage colony-stimulating factor (M-CSF/CSF1) secreted by tumor cells." (PMID 38242119, 2024). "PLX647 improves systematic immunosuppressive state by inhibiting CSF1/CSF1R signaling and has been shown to be effective in the treatment of breast cancer, melanoma and lung cancer." (PMID 36439090, 2022). "Colony-stimulating factor 1 (CSF1) is a monocyte/macrophage differentiation regulator factor, expressed in human melanoma, which sustains the protumorigenic mechanism of tumor-associated macrophages." (PMID 35742834, 2022). "In a recent study it was shown that, tumor derived factors such as colony stimulating factor-1 (CSF-1), CCL-2, IL-34, and VEGF recruit circulating macrophages to the melanomas." (PMID 31134198, 2019). "In murine melanoma models driven by BRAFV600E, anti-CSF1 inhibitors alone displayed modest efficacy, yet dual blockade of anti-CSF1 and anti-PD-1 regressed 100% of tumors by 17 days, with 90% survival after 90 days." (PMID 30191140, 2018). "We used the syngeneic mouse model of BRAFV600E-driven melanoma SM1, which secretes CSF-1, to evaluate the ability of the CSF-1 receptor (CSF-1R) inhibitor PLX3397 to improve the antitumor efficacy of the oncogenic BRAF inhibitor vemurafenib." (PMID 25939769, 2015). "Interestingly, many known melanoma-related genes like VEGF, SPP1, and CSF1 have been included in the 103 LR pairs selected by SpatialDM." (PMID 37414760, 2023).
melanoma (continued). "Additionally, CSF1 expression correlates with accumulation of CD8+ T cells and CD163+ TAMs in melanoma, and anti−PD1 and anti−CSF1R combination therapy induced regression of melanoma in preclinical studies." (PMID 35664746, 2022). "In a study assessing melanoma and NSCLC, both tumors with high immune infiltration, researchers found that non-mature CD1c+ CD14- cDC2s could be directed towards DC3s (CD1c+ CD14+ cDC2s) through tumor-derived IL-6 and M-CSF (CSF1)." (PMID 40584260, 2025). "Furthermore, the extent of correlation of CSF1 with immune checkpoint genes was in concert with recent data implicating CSF1 as a CD8+ T-cell-dependent adaptive resistance mechanism to PD-1 blockade and showing that simultaneous CSF1R targeting may be beneficial in melanomas refractory to ICB." (PMID 37404751, 2023).
lung cancer (46 papers, 1999 to 2026). A malignant neoplasm involving the lung. "In lung cancer, the expression levels of CSF1 and SPP1 are increased and associated with the carcinogenesis and prognosis of patients." (PMID 37097499, 2023). "The association between Vav1 expression and CSF1 was further supported by signal transduction experiments, pointing to the involvement of Vav1 in regulating the lung cancer secretome." (PMID 26353933, 2015). "The association between Vav1 expression and CSF1 was further supported by signal transduction experiments, supporting involvement of Vav1 in regulating lung cancer secretome." (PMID 25313137, 2014). "Chemoresistant lung cancer cells secrete IL‐34, which is associated with immune suppression by inducing the M2‐like phenotype of TAMs,37 and co‐expression of IL‐34 and CSF‐1 in cancer cells is correlated with a worse clinical course in patients with lung cancer." (PMID 35132816, 2022). "In lung cancer, CSF1 is one member of a three-gene signature strongly associated with poor prognosis in early-stage squamous cell carcinoma and its level of expression significantly increases with disease progression in Non Small Cell Lung Carcinoma (NSCLC) patients." (PMID 25313137, 2014). "Dominant overexpression of Sh3glb1, Tm4sf1 or Csf1 in chromosome 3 of TCs is mainly associated with tumour promotion in lung cancer, while most down-expression of Pde5 may be involved in the development of pulmonary fibrosis and other acute and chronic interstitial lung disease." (PMID 25278030, 2014). "Additional studies demonstrated the involvement of the MEK/ERK pathway and PI-3K signaling in CSF-1-mediated proliferation, invasion and survival of lung cancer cell lines." (PMID 38254773, 2024). "In the H358 lung cancer cell line, CSF1 knockdown resulted in significantly smaller tumors that exhibited increased fibrosis and decreased tumor-infiltrating macrophages." (PMID 37174676, 2023). "In lung cancer, it participates in macrophage function control and facilitates the release of proinflammatory chemokines throughout its target colony stimulating factor 1 (CDF1); it can also inhibit STAT3 and AKT signaling." (PMID 38146340, 2023). "Vav1 instigated TME by fibrosis enhancement and reduction in tumor infiltrating macrophage, which was due to cross-talking with colony-stimulating factor 1 (CSF1) pathway, favoring lung cancer growth." (PMID 37033636, 2023). "M1 macrophages promote lung cancer to express octamer 4 (Oct4) to upregulate CSF-1 gene expression, and CSF-1 stimulates the activation of M2 macrophages." (PMID 35740975, 2022). "We found that CCL3, CCL4, and CSF1 were significantly upregulated in IL17D–expressing human lung cancer cells, whereas Ccl3, Ccl4, and Il6 were induced in IL17D–expressing murine lung cancer cells." (PMID 35939336, 2022). "Over-expression of JunB Proto-oncogene increases the involvement of EMT in the invasion and metastasis of lung cancer; Colony-stimulating factor 1 (CSF1) increases the proliferation and invasion of lung cancer cells." (PMID 35910766, 2022). "Depletion of CSF1 in lung cancer cells led to decreased proliferation and focus-formation in vitro, as well as diminished tumor growth in immune-compromised mice, suggesting that CSF-1 secretion is cardinal for tumorigenicity." (PMID 35326399, 2022). "Serum CSF1 is increased in patients with lung cancer, and knockdown of CSF1 reduces osteoclasts and improves bone metastasis." (PMID 32801364, 2020). "We next used MIRUMIR (a database for survival analyses in cancer) and analyzed the clinic impact of CSF1 expression patterns on lung cancer patients survival." (PMID 27107415, 2016). "In the current study we identified a novel target gene CSF1 for miR-1207-5p, and investigated its role in tumorigenesis of lung cancer." (PMID 27107415, 2016). "miR-1207-5p and CSF1 expression levels and their relationship with lung cancer survival and metastasis status were assayed by means of a lung cancer tissue microarray." (PMID 27107415, 2016).
lung cancer (continued). "We tested seven representative lung cancer cell lines for the expression of CSF-1R and its ligands, CSF-1 and IL-34." (PMID 27486763, 2016). "Since almost all of the lung cancer cell lines in our collection exhibited CSF-1/CSF-1R expression, we focused on the CSF-1/CSF-1R duo for the subsequent experiments." (PMID 27486763, 2016). "Here, we started from the observation that the secretome of cisplatin treated lung cancer cells is enriched for the CSF-1R ligand, CSF-1, which was secreted by almost all the lung cancer cell lines in our collection." (PMID 27486763, 2016). "miR-1207-5p can inhibit CSF1 mRNA/protein expression and secretion in lung cancer cell A549 by targeting the 3′-UTR of the CSF1 mRNA." (PMID 27107415, 2016). "Similar results were obtained in breast, ovarian and lung cancers where a CSF-1 dependent autocrine loop contributes to tumor invasiveness and metastasis." (PMID 25886010, 2015). "We found that lung cancer cells depleted of Vav1 exhibit significantly reduced levels of the hematopoietic growth factor CSF1, suggesting that Vav1 propagates an autocrine feed forward loop by upregulating expression of growth factors." (PMID 26353933, 2015). "This intricate signaling pathways in which Vav1 and CSF1 are involved results on one hand in control of CSF1 expression in lung cancer cells and on the other hand, Vav1 stimulation by CSF1, thus evoking cytoskeleton organization and increased tumorigenicity." (PMID 25313137, 2014). "One of the most intriguing results from our current studies is that lung cancer cells depleted of Vav1 exhibit significantly reduced levels of CSF1, suggesting that Vav1 propagates an autocrine feed forward loop by upregulating expression of growth factors." (PMID 25313137, 2014). "To investigate this possibility, we explored the signaling events triggered by CSF1 stimulation in lung cancer cells." (PMID 25313137, 2014). "Remarkably, we found a significant positive correlation between expression of Vav1 and CSF1 in these primary human lung cancer specimens (p<0.05)." (PMID 25313137, 2014). "Our current studies demonstrate for the first time, that Vav1 is tyrosine phosphorylated in response to CSF1 in lung cancer cells, thus suggesting a supportive role for Vav1 as a universal signal transducer in cancer." (PMID 25313137, 2014). "Similar to our results with CSF1, in lung cancer cell lines, TGFα leads to an increase in tyrosine phosphorylation of Vav1, while depletion of Vav1 reduces TGFα expression." (PMID 25313137, 2014). "CSF1-depleted lung cancer cells demonstrate reductions in proliferation and focus-formation in vitro and reduced tumor growth in immune-compromised mice, indicating that CSF1 expression and secretion is cardinal for tumorigenicity." (PMID 25313137, 2014). "Similarly, the administration of CSF-1 enhanced the invasive potential of lung cancer both in vivo and in vitro." (PMID 38254773, 2024). "Furthermore, VAV1 and CSF1 expression were positively correlated with tumor grade by immunohistochemical analysis of primary human lung cancers." (PMID 37174676, 2023). "For example, tumor-cell-secreted factors like CCL2 and CSF1, contribute to the recruitment and survival of TAMs, which in turn promote immune evasion, cancer proliferation, epithelial-mesenchymal transition, and tumor invasiveness in lung cancer." (PMID 37656220, 2023). "Similarly, in lung cancer cells, CSF-1 level and duration of stimulation controlled the cell invasiveness." (PMID 36555673, 2022). "First, it has been found that the expression of colony stimulus factor 1 (CSF-1) and interleukin-6 (IL-6) in non-small cell lung cancer (NSCLC) is closely associated with the infiltration of TAMs in tumor stroma and the progression of lung cancer." (PMID 33224886, 2020). "Thus, multiple lung cancer cell lines expressed detectable amount of CSF-1R and its ligand CSF-1, thus suggesting that they are capable of CSF-1R signaling." (PMID 27486763, 2016).
lung cancer (continued). "Macrophage is an essential part of the tumor microenvironment, thus the miR-1207-5p-CSF1 axis maybe a new regulator of lung cancer development through modulating the tumor microenvironment." (PMID 27107415, 2016). "Thus, lung cancer cells express a functional CSF-1 and CSF-1R duo which mediates pro-tumorigenic effects in vivo and in vitro and can be targeted in a therapeutically relevant way." (PMID 27486763, 2016). "Then, we stimulated H358 lung cancer cells, known to express high levels of Vav1, with CSF1." (PMID 25313137, 2014). "Indeed, depletion of Vav1 in lung cancer cells led to reduced ERK phosphorylation despite stimulation with CSF1." (PMID 25313137, 2014). "As these results suggest that CSF1 may be a major mediator of a Vav1 dependent loop, we next wished to determine whether CSF1 leads to Vav1 tyrosine phosphorylation in lung cancer cells." (PMID 25313137, 2014). "Our preliminary results pointed to the possibility that lung cancer cells that ectopically express Vav1 (H358) also secrete CSF1, a hematopoietic growth factor that stimulates monocyte proliferation and differentiation into macrophages and can activate Vav1 in immune cells." (PMID 25313137, 2014). "Thus, it has been suggested that lung cancer may involve interactions between cancer cells and the microenvironment regulated via the CSF1/VAV1 signaling pathway." (PMID 37174676, 2023). "Thus, lung cancer cell lines could upregulate CSF-1 mRNA and protein and secrete CSF-1 in the medium after cisplatin treatment." (PMID 27486763, 2016). "Our results indicate that a CSF1-Vav1 pathway may contribute to lung cancer development." (PMID 25313137, 2014). "Overexpression of TM4SF1 and Csf1 in lung TCs may have a role in the development of lung cancer." (PMID 25278030, 2014). "Thus, combined Vav1 and CSF1 expression correlates with tumor grade in human lung cancer samples, providing support for the hypothesis that Vav1 and CSF1 might have converging roles in lung cancer development." (PMID 25313137, 2014). "Finally, the correlation we observed between combined Vav1 positive/CSF1 positive expression and tumor grade further strengthens our conclusion that these proteins act together in a feed-forward loop that contributes to tumorigenicity in human lung cancer." (PMID 25313137, 2014). "Thus, expression of CSF1 is critical for the tumorigenic properties of H358 lung cancer cells." (PMID 25313137, 2014). "Intervention of the CSF1/CSF1R and IL-6/IL-6R ligand-receptor pairs significantly reduced the ability of CHI3L1 lung cancer cells to recruit macrophages." (PMID 41362730, 2026). "MPE-Mφ showed relatively higher expression levels of M1 (IL-1β, IL-6, and CXCL10), M2 (CCL18 and IL-10), and pan-macrophage markers (CSF1 and PTPRC) compared to MDMs from lung cancer patients or HCs." (PMID 33175182, 2021). "Indeed, the high expression of IL-34 and CSF-1 in lung cancer tissues is intimately related to the progression of lung cancer, which suggests that IL-34 and CSF-1 secreted by tumor cells may activate and maintain the pro-tumor function of TAMs by interacting with the CSF1R receptor on TAMs." (PMID 33224886, 2020). "First, quantitative PCR of mRNA obtained from 4 representative lung cancer cell lines (H1975, NCI-H1299, A549 and Calu-1) revealed that both the receptor and the ligand CSF-1 mRNAs were steadily increased by cisplatin treatment (24 hrs, CC50)." (PMID 27486763, 2016). "The study found that in the animal model of lung cancer, knocking out or blocking CSF1/CSF1R will significantly reduce the number of TAMs, proving that blocking the survival signal of macrophages was one of the effective ways to prevent and treat lung cancer." (PMID 37006240, 2023). "The mRNA expression of CCL3, CCL4, and CSF1 was significantly upregulated in IL17D–expressing A549 cells compared with that in control cells, whereas IL17D overexpression in the murine lung cancer cell line LLC1 increased Ccl3, Ccl4, and Il6 expression." (PMID 35939336, 2022).
lung cancer (continued). "Also, diminished Vav1′s expression in lung cancer cell lines reduced the expression of the growth factors, TGFα and EGF, and CSF-1, which led to reduced tumorigenicity." (PMID 35326399, 2022). "Our present work shows MLN4924-treated lung cancer cells had lower gene expression of CCL2 and CSF1 (data not shown) than controls, suggesting that CCL2, CSF1 may participate in modulating the TAM infiltration in LUAD." (PMID 37656220, 2023).